PMS2 (PMS1 homolog 2, mismatch repair system component)
Diseases named in the same sentence as PMS2 in open-access papers (continued):
Sharing a sentence is not in itself a finding about the gene and the disease.
Lynch syndrome (continued). "Heterozygous germline mutations in the mismatch repair genes including MLH1 and PMS2 can cause Lynch syndrome, an autosomal dominant cancer predisposition syndrome conferring a high risk of colorectal, endometrial, and other cancers in adulthood." (PMID 30370249, 2018). "PMS2 is commonly included on HCS panels due to its association with Lynch syndrome, though HCS panels often require orthogonal techniques to identify variants located in PMS2." (PMID 30268105, 2018). "Meanwhile, germline mutations of MSH6 and PMS2 accounts for 7–10% and less than 5% cases of Lynch syndrome respectively." (PMID 28903413, 2017). "The MutLα heterodimer formed by mismatch repair proteins MLH1 and PMS2 is a major component of the mismatch repair complex, yet mutations in the PMS2 gene are rare in the etiology of Lynch syndrome." (PMID 28347324, 2017). "The identification of the proband’s homozygous PMS2 mutation status has led to the diagnosis of several family members with Lynch syndrome." (PMID 28381238, 2017). "Accounting for the relatively small frequence of PMS2 mutations (up to 8% of all Lynch syndromes) there is a relatively small probability that it would influence the results of our work." (PMID 26485756, 2015). "For example, PMS2 mutations are nowadays considered as other potential mechanisms of familial colorectal cancer syndromes akin to the more common Lynch Syndrome." (PMID 26485756, 2015). "Germline mutations in the MMR genes MLH1, MLH2, MSH6, and PMS2 can lead to the development of Lynch syndrome, and heterozygosity for a mutation in one of these genes can result in increased susceptibility to cancer." (PMID 26064726, 2015). "Larger numbers of Lynch syndrome families and screening of the two additional predisposition genes, PMS2 and EPCAM, are needed in order to decipher the full spectrum of mutations associated with Lynch syndrome predisposition in Cyprus." (PMID 25133505, 2014). "Mutations in PMS2 lead to Lynch syndrome (LS), an autosomal genetic disease with a high risk of colon cancer." (PMID 25018888, 2014). "This underlines the importance of EPCAM deletions in the Lynch syndrome, as it is a more frequent cause of LS than mutations in PMS2 or MSH6." (PMID 23938213, 2013). "The next closest – located approximately 1,500 bp downstream from the breakpoint we describe – also generated a deleterious hybrid PMS2 allele associated with Lynch syndrome." (PMID 22585707, 2012). "We used this approach to identify the presence of PMS2 deletions in germline DNA from 13 patients whose colorectal tumors were suspected to be caused by PMS2-related Lynch syndrome." (PMID 22585707, 2012).
Lynch syndrome (continued). "Phenotype information for MSH6 and PMS2 mutation carriers is therefore of great interest for the recognition of Lynch syndrome and the formulation of sufficient surveillance schemes." (PMID 20487569, 2010). "Novel MSH6 and PMS2 mutations are being reported and submitted to the current databases for identified Lynch syndrome mutations." (PMID 20487569, 2010). "MSH6 and PMS2 mutations represent 10.3% and 1.9%, respectively, of the pathogenic mutations in our Australian Lynch syndrome families." (PMID 20487569, 2010). "Although the PMS2 gene is crucial in the repair system, mutations have rarely been reported in the etiology of the Lynch syndrome, or in Turcot syndrome (one of the variants of Lynch syndrome)." (PMID 19466295, 2009). "Furthermore, a 3-year surveillance interval is more cost-effective for patients who have Lynch syndrome with MSH6 or PMS2 as the causative gene." (PMID 41214301, 2026). "Similarly, isolated MSH6 or PMS2 loss should trigger consideration of genetic counseling and germline testing to identify individuals at risk for Lynch syndrome." (PMID 41462964, 2025). "Given her personal history of multiple cancers and family history of cancers, she was referred to cancer genetics and pursued genetic testing with a 91-gene panel (Ambry Laboratories), demonstrating a germline PMS2 pathogenic variant (EX8del) consistent with Lynch syndrome." (PMID 39188332, 2024). "PMS2 was also reported to be the most frequently mutated Lynch syndrome gene in endometrial cancer." (PMID 38200495, 2024). "Our study identified one germline P/LP Lynch Syndrome variant (PMS2)." (PMID 39516637, 2024). "Similarly, BRCA1, BRCA2 and PMS2 were also reported as germline mutations in cancers other than Lynch syndrome and HBOC." (PMID 36451132, 2022). "However, inactivation of MLH1 or PMS2 alleles are the most frequent ones and are associated with approximately 80% of Lynch syndrome cases." (PMID 34630437, 2021). "One pathogenic variant in PMS2 associated with Lynch syndrome was also identified in this study." (PMID 32231684, 2020). "The findings in MSH6 and PMS2 are of particular clinical importance, as these data are extremely limited in the literature until recently, yet clinicians counsel about a general increased risk for ovarian cancer with PVs in Lynch syndrome genes." (PMID 31406321, 2020). "In addition, 3 patients had pathogenic variants in the Lynch syndrome-associated genes PMS2 (n = 2) and MLH1 (n = 1)." (PMID 32090079, 2020). "In our cohort, 14% (12/83) of the Lynch syndrome patients were PMS2 mutation carriers." (PMID 28933000, 2018). "Around 15% of all Lynch syndrome cases are estimated to be caused by PMS2 mutations." (PMID 28933000, 2018). "The results of our study indicate that while the models MMRpredict and PREMM5 can adequately predict whether an individual is likely to have Lynch syndrome, they fail to identify PMS2 mutation carriers." (PMID 28933000, 2018). "Isolated loss of PMS2 is rare in patients with Lynch syndrome." (PMID 28699072, 2017). "Heterozygous PMS2 mutations appear to display an attenuated Lynch syndrome phenotype." (PMID 28381238, 2017).
Lynch syndrome (continued). "Thus, the two MutL homologs are partially redundant, possibly explaining the 40:1 ratio of MLH1 to PMS2 gene mutations seen in Lynch syndrome tumors." (PMID 23450065, 2013). "PMS2 has previously been reported to be associated with Lynch Syndrome and colorectal cancer." (PMID 22745689, 2012). "Heterozygous PMS2 germline mutations are associated with Lynch syndrome." (PMID 22585707, 2012). "Notwithstanding, some information is available with respect to the frequency of MSH6 and PMS2 mutations but there is relatively limited information available regarding the spectrum of disease, especially in Australian Lynch syndrome families harbouring deleterious changes in one of these two genes." (PMID 20487569, 2010). "However, whether this microsatellite shift pattern can serve as a reliable indicator for isolated PMS2 loss or PMS2-associated Lynch syndrome requires further investigation." (PMID 41041321, 2025). "Delayed oophorectomy also may currently be taken into consideration in the case of other gene mutations predisposing patients to gynecological malignancies, such as MLH1, MSH6, and PMS2 in Lynch syndrome and PALB2, whose cancer risk range estimates overlap with BRCA." (PMID 36835955, 2023). "This is known to be relatively common in cases of Lynch syndrome with an MLH1 variant, and only PMS2 expression is lost in most of these cases." (PMID 41214301, 2026). "CNV detection in genes such as PMS2 (Lynch syndrome) and SMN1 (Spinal Muscular Atrophy) is notoriously challenging because of high-similarity paralogs (PMS2CL and SMN2) that cause nonspecific read alignment and distorted read depth." (PMID 41595524, 2026). "One case exhibited isolated MSH6 loss, suggesting a potential Lynch syndrome, and another showed combined MSH6/PMS2 loss." (PMID 41462964, 2025). "An additional mechanism causing MLH1/PMS2-deficiency is constitutional monoallelic MLH1 gene promoter hypermethylation (MLH1 epimutation), a form of Lynch syndrome, which has been shown to be rare." (PMID 40208414, 2025).
Lynch syndrome (continued). "Different methodologies, such as single-marker versus multi-marker MSI panels and varied IHC protocols, can affect the detection rates of Lynch syndrome, especially for subtler MSH6 and PMS2 mutations known for their heterogeneous expression." (PMID 40244260, 2025). "Since only a variant of uncertain significance (VUS) in PMS2 was detected in the MMR germline mutation analysis, Lynch syndrome was excluded." (PMID 41278281, 2025). "This formed the basis for selecting pembrolizumab as the neoadjuvant immunotherapy agent in the current patient, with the patient having known Lynch syndrome and immunohistochemical analysis of the tumour biopsy confirming deficiencies in MLH1 and PMS2." (PMID 40341577, 2025). "This is due to the relatively high rates of germline Lynch syndrome mutations in individuals with dMMR staining (25–67%); however, a common alternative etiology for dMMR involving MLH1 and PMS2 is sporadic MLH1 promoter methylation." (PMID 40002254, 2025). "Future validation through larger prospective cohort studies is necessary to confirm our findings and better understand the natural history of PMS2-CMMRD to inform clinical decision-making in PMS2-Lynch syndrome (PMS2-LS)." (PMID 41333974, 2025).
Lynch syndrome (continued). "Conversely, we reported a child with “POLE-Lynch syndrome” carrying a de novo PMS2 DCV and inherited POLE DCV, manifested by an aggressive medulloblastoma with a unique genomic signature." (PMID 39546165, 2024). "PMS2 and MLH1 are key genes whose inactivation causes Lynch syndrome, involving colorectal, endometrial, and other cancers." (PMID 38609352, 2024).